ATF6 (activating transcription factor 6)
Diseases named in the same sentence as ATF6 in open-access papers (continued):
Sharing a sentence is not in itself a finding about the gene and the disease.
colitis (10 papers, 2012 to 2025). Inflammation of the colon. "Specifically, the loss of PCDH20 impairs intestinal barrier function by unzipping adherens junctions in mice with colitis via targeting the ATF6/CHOP/β-catenin/p120-catenin axis." (PMID 37407995, 2023). "We found that AA147 administration reverses elevated CHOP expression, barrier defects, and colitis susceptibility in Pcdh20 CKO mice with colitis, by selectively increasing both cleaved and 90kd fragments of ATF6." (PMID 37407995, 2023). "Nevertheless, the expression of the CHOP/β-catenin/p-p120-catenin was partly rescued by cleaved ATF6 activated via AA147 administration in the Pcdh20 CKO mice and the PCDH20-deficient cell lines during colitis." (PMID 37407995, 2023). "Specifically, PCDH20 helps to protect against colitis by tightening adherens junctions through the ATF6/CHOP/β-catenin/p-p120-catenin axis." (PMID 37407995, 2023). "The finding that IL-10-mediated p38 signaling inhibited TNF-induced recruitment of ATF6 to the Grp78 promoter provides a plausible explanation for colitis development in IL10−/− mice." (PMID 31867005, 2019). "ATF6 expression can boost the expression of inflammatory cytokines and provoke intestinal inflammation by triggering the NF-κB signaling pathway regulating inflammatory gene expression, which aggravate the development of colitis." (PMID 40359212, 2025). "Moreover, mutations in the ATF6 activator, S1P, disrupt ATF6 expression and the UPR, thus, increasing the sensitivity to colitis in mice." (PMID 37407995, 2023). "As there is considerable evidence for the induction of the UPR in colitis, this appears to recognize that parallel responses, controlled by the activating transcription factor 6 or inositol-requiring enzyme 1α (IRE1α), can compensate for the loss of PERK independent of eIF2α phosphorylation." (PMID 36875104, 2023). "Moreover, ATF6 was downregulated in the colonic epithelium of PCDH20-deficient patients with CD and Pcdh20 CKO mice with colitis." (PMID 37407995, 2023). "By administering a selective ATF6 activator, the impairment of intestinal barrier integrity and dysregulation of CHOP/β-catenin/p-p120-catenin pathway was reversed in Pcdh20-ablated mice with colitis and PCDH20-deficient colonic cell lines." (PMID 37407995, 2023). "Immunohistochemistry (IHC) of ATF6 were analyzed in 137 surgically resected CRCs, 95 endoscopically resected adenomas and pTis cancers, and 136 samples from 51 UC patients (93 colitis without neoplasia, 31 dysplasia, and 12 UC-associated CRC)." (PMID 28884228, 2018). "However, the induction of colitis by TNBS resulted in significant increases in the mRNA levels of ATF6, ATF4, BiP and CHOP, both at 2 d and 7 d." (PMID 23209735, 2012). "Similar to our findings, Atf6-knockout mice exhibited increased susceptibility to experimental colitis, characterized by a larger ulceration area and elevated expression of CHOP, which has been reported as a major apoptotic factor in an UPR and an aggravating factor in colitis." (PMID 37407995, 2023). "Moreover, we unveiled that ATF6 is essential for paracellular permeability in vitro during colitis." (PMID 37407995, 2023). "Thus, PCDH20 deficiency could impair epithelial barrier function by downregulating ATF6 in colitis." (PMID 37407995, 2023). "We demonstrate that PCDH20 deficiency unzips the adherens junctions between enterocytes by suppressing the ATF6/CHOP/β-catenin/p120-catenin pathway, thereby disrupting barrier integrity and enhancing sensitivity to experimental colitis." (PMID 37407995, 2023). "It is reported that Shaoyao decoction enhanced the Muc2 levels in the colon of the DSS-induced colitis model, and Angelica sinensis protected H9C2 cells against ER stress by activating the ATF6 pathway." (PMID 36010498, 2022).
colitis (continued). "Consistently, GP supplementation reduced the protein expression of ATF-6 and mRNA expression of its downstream target genes Grp78, CHOP, Edem1, and Xbp1 in the HFD-fed DSS-colitis mice, showing the suppression of ER stress." (PMID 28524086, 2017). "Moreover, we found that PCDH20 deficiency disrupted the intestinal barrier function by suppressing the ATF6-mediatied ER stress pathway in colitis, which indicated that PCDH20 reduction played a significant role in intestinal inflammation dependent on ATF6." (PMID 37407995, 2023). "Numerous models with perturbations in the UPR pathways (ATF6, p58IPK, IRE-1, CHOP, OASIS, and S1P) do not show spontaneous phenotypes but display increased susceptibility to DSS-induced colitis." (PMID 31867005, 2019). "Notably, there was an obvious difference between the rate of ATF6-IHC positivity in LGD (70.8%) and that in inactive (17.9%, p < 0.001) and active colitis (24.1%, p < 0.001)." (PMID 28884228, 2018). "Experimentally, Ire1β−/− and Atf6α−/− mice treated with dextran sulfate sodium (DSS), which is cytotoxic to intestinal epithelial cells and widely accepted to induce colitis in mouse models, show early development of colitis." (PMID 24498426, 2014). "It should be noted that the ATF6-IHC score in LGD (median, 6.0, range, 2–12) was significantly different (p < 0.001) from the one in non-neoplastic lesions, i.e., inactive and active colitis samples (median, 3.0, range, 0–8, and median, 3.0, range, 0–11, respectively)." (PMID 28884228, 2018).
gastric cancer (10 papers, 2014 to 2025). A primary or metastatic malignant neoplasm involving the stomach. "Previous studies have shown that macrophage lineage cell-derived migrasomes activate complement-dependent BBB damage, and gastric cancer migrasomes carrying the ATF6 protein disrupt BBB integrity." (PMID 41241718, 2025). "ATF6 is suggested to confer a multidrug resistance phenotype to gastric cancer cells by deactivating SIRT1." (PMID 38606478, 2024). "One study shows that JAK2 or STAT3 inhibitor reduces 5-FU resistance and autophagy through ATF6-mediated ER stress in gastric cancer cells, which also enhances the sensitivity of gastric cancer cells for 5-FU." (PMID 38536006, 2024). "Furthermore, a time-course experiment directed by actinomycin D, an inhibitor of transcription, revealed that the stability of circ0007360 was significantly higher than ATF6 mRNA in both gastric cancer cell lines." (PMID 35252169, 2022). "Besides, gastric cancer patients with higher expression of either ATF6 or SP1 had poor survival rates which suggested that these genes might act as a potential biomarker for diagnosis." (PMID 37848946, 2023). "Interestingly, ATF6 and SP1 RNA transcripts negatively correlated with ages in patients with gastric cancer." (PMID 37848946, 2023). "Although endoplasmic reticulum stress caused by sirtuin inhibitors was reported to induce DR5 up-regulation in other cancer cell lines, we could not find marked activation of its related molecules, such as ATF6, PERK, and CHOP, in gastric cancer cells treated with tenovin-6." (PMID 25033286, 2014).
myocardial infarction (10 papers, 2019 to 2023). Gross necrosis of the myocardium, as a result of interruption of the blood supply to the area, as in coronary thrombosis. "Furthermore, ATF6 gain-of-function mice exhibits an alleviated myocardial infarction after I/R injury demonstrating that ATF6 is required to protect the heart from damage and injury caused by myocardial infarction." (PMID 37373035, 2023). "Similar to that observed in ATF6 and Xbp1s overexpression mouse models, in vivo gain-of-function of Ire1 results in preserved cardiac function and reduced fibrosis after myocardial infarction." (PMID 37373035, 2023). "A subsequent study that also indicated that ATF6 reduces damage in the heart, examined the effects of ATF6 inhibition using either a chemical inhibitor of ATF6 or transgenic overexpression of dominant negative ATF6 in a mouse model of myocardial infarction." (PMID 32322217, 2020). "Here, we found that, compared to control mouse hearts, αSMA and Col1a1 were significantly elevated in the hearts of ATF6 knockout (KO) mice subjected to myocardial infarction." (PMID 32085622, 2020). "Here, we show that genetic markers of fibroblast activation, such as αSMA, are elevated in the heart following a myocardial infarction and that ATF6 deletion enhances this induction." (PMID 32085622, 2020). "Data presented by Toko and collaborators showed that inhibition of ATF6 with 4-(2-aminoethyl) benzenesulfonyl fluoride or knockdown of ATF6 with siRNA decreased cardiac function, increased myocardial infarction mortality rate, and increased cardiomyocyte apoptosis in mice." (PMID 38283278, 2023). "Myocardial infarction causes the abnormal activation of the UPR and the significantly increased expression of ERS proteins, including GRP78, PERK, ATF6, XBP1, and p-PERK, indicating that myocardial infarction triggered the excessive activation of the ERS pathway." (PMID 34765006, 2021). "Furthermore, treatment of myocardial infarction-induced mouse with ATF6 inhibitor, 4-(2-aminoethyl)benzenesulfonyl fluoride, further reduced cardiac dysfunction and increased mortality rate." (PMID 31551782, 2019). "Treadmill exercise training can reduce GRP-78, p-PERK, p-eIF2α, ATF-6, XBP1, CHOP, and cleaved-caspase-3 expression to improve the cardiovascular function and reduce myocardial infarction in rats." (PMID 34987702, 2021). "This phenomenon was made manifest when mouse hearts without ATF6 subjected to myocardial infarction showed greater induction of fibroblast activation markers in comparison to their WT counterparts." (PMID 32085622, 2020).
Sepsis (10 papers, 2017 to 2026). Sepsis is defined as life-threatening organ dysfunction caused by a dysregulated host response to infection. "Endoplasmic reticulum (ER) stress caused by MV, oxidative stress, and sepsis results in dissociation of GRP78 from transmembrane proteins (PERK, IRE1α, and ATF6) and generates abundant incorrect protein structures." (PMID 40565223, 2025). "The protein expression level of p90 ATF6 was markedly reduced, with a concomitant increase in the p50 ATF6 component in the sepsis group (P = 0.0014, P = 0.0015, respectively)." (PMID 36088483, 2022). "Meanwhile, the uncleaved p90 ATF6 was markedly reduced and cleaved p50 ATF6 was increased in the sepsis group." (PMID 36088483, 2022). "The cleaved soluble transcription factor p50 ATF6 was significantly increased in the sepsis group, then free to translocated to the nucleus where it subsequently activated ER stress responsive genes, such as GRP78, GRP94, calreticulin, and CHOP44." (PMID 36088483, 2022). "After treated with TAK-242, the cleavage of ATF6 was significantly reduced compared with the sepsis group (P = 0.0098, P = 0.0261, respectively)." (PMID 36088483, 2022). "Consequently, Cd11ccreRetreg1fl/fl, Retreg1-/-, and Atf6-/- mice exhibit impaired DC function, leading to immunosuppression and multiple organ failure in experimental sepsis." (PMID 41874459, 2026). "We found that sepsis of CLP induced the cleavage of ATF6 in the small intestine." (PMID 36088483, 2022). "In addition, our data showed that GRP78, CHOP, and ATF6 were over-expressed in patients with severe sepsis that led to death via calculating the mean fluorescence intensity in flow cytometry, which was further verified by immunofluorescence in another cohort." (PMID 34326834, 2021). "It is also possible that, among UPR pathways, ATF6 is the most intensely involved pathway during sepsis but additional experiments should be carried out to study this hypothesis before drawing any conclusion." (PMID 31737637, 2019). "Furthermore, CLP-induced sepsis induced the cleavage of ATF6 in the small intestine." (PMID 36088483, 2022). "Furthermore, our findings suggested that TLR4-mediated the hyperactivation of ER stress, via activating the ATF6/CHOP pathway, might be one of the mechanisms associated with Paneth cells loss and dysfunction during intestinal barrier impairment of sepsis." (PMID 36088483, 2022). "In the present study, we demonstrated that ERS participated in sepsis-induced cardiac dysfunction in infant rats and that the levels of proteins, including GRP78, ATF6, p-PERK, PERK, p-IRE-1a, and IRE-1a were significantly increased by CLP." (PMID 39907066, 2025). "The PERK–ATF4 signaling pathway is one of the indispensable ERS signaling pathways in addition to the IRE1–XBP1 and ATF6 pathways, all of which can lead to the transcription of CHOP, a pivotal mediator in the development of sepsis." (PMID 36873287, 2023). "We observed that compared with the control group, the mRNA levels of ATF6 and XBP1 were elevated in the sepsis group." (PMID 36088483, 2022). "The present results suggested that compared with the control group, the result of real-time PCR revealed the mRNA expression level of ATF6 and XBP1 both were increased in the sepsis group (both P < 0.0001) and dramatically decreased in the treatment group (P = 0.0003, P < 0.0001, respectively)." (PMID 36088483, 2022). "Of note, the expression levels of ATF6, XBP1 and CHOP increased in the ileal of the sepsis group." (PMID 36088483, 2022). "In a mouse model of sepsis combined with ALI, researchers found that VD improves the lung tissue structure, neutrophil infiltration, endothelial barrier, and reduces the upregulation of ER stress markers activating transcription factor 6 (ATF6) and C/EBP homologous protein induced by CLP and LPS." (PMID 40728969, 2025).
Sepsis (continued). "More importantly, in this study we discovered TLR4 inhibitors(TAK-242) could improve various indicators of excessive ER stress, inculding downregulating the level of ATF6 mRNA, reducing the cleavage of ATF6 and in turn reducing the expression of CHOP compared with the sepsis group." (PMID 36088483, 2022).
ischemia (9 papers, 2015 to 2023). A hypoperfusion of the BLOOD through an organ or tissue caused by a PATHOLOGIC CONSTRICTION or obstruction of its BLOOD VESSELS, or an absence of BLOOD CIRCULATION. "MANF mRNA and protein were induced on ATF6 activation in the myocardium, in vivo, consistent with the hypothesis that ER stresses, such as ischemia, which can activate ATF6, a hallmark of ER stress genes, might also induce MANF expression in the heart." (PMID 28536652, 2017). "AA147, originally developed as a pharmacologic activator of the activating transcription factor 6 (ATF6), can protect multiple tissues from ischemia/reperfusion injury (IRI) by decreasing reactive oxygen species (ROS) and restoring ER function." (PMID 36506549, 2022). "For instance, activation of the ATF6α branch before ischemia reduces myocardial tissue damage during ischemia/reperfusion." (PMID 26729106, 2015). "Transgenic mouse models that specifically targetted the ATF6 branch in cardiomyocytes have shown that activation of ATF6 decreased myocardial damage after ischemia and/or reperfusion, while disruption of endogenous ATF6 increased pro-apoptotic signaling and aggravated cardiac function." (PMID 30232231, 2018).
liver cancer (9 papers, 2014 to 2026). An epithelial or non-epithelial malignant neoplasm that arises from the liver. "Thus, prolonged ATF6α activation drives ER stress, leading to glycolysis-dependent immunosuppression in liver cancer and sensitizing to ICB." (PMID 41639449, 2026). "We provide first evidence that SND1 promoter activity is increased in human liver cancer cells upon exposure to thapsigargin or tunicamycin or by ectopic expression of ATF6, a crucial transcription factor in the unfolded protein response triggered by ER stress." (PMID 25494629, 2014). "Targeting Atf6 through germline ablation, hepatocyte-specific ablation or therapeutic hepatocyte delivery of antisense oligonucleotides dampened HCC in preclinical liver cancer models." (PMID 41639449, 2026). "In summary, the mechanisms by which cytisine, gecko polypeptide mixture, muscone, and others induce apoptosis in liver cancer cells are mainly the PERK, IRE1, and ATF6 pathways, and HepG2 cells are the primary cell line that has been studied." (PMID 38044941, 2023). "In liver cancer ATF6 is also responsible for upregulation of XBP1 expression and the activity of both ATF6 and XBP1 increases BiP expression, leading to hepatocarcinogenesis." (PMID 26491226, 2015). "Our study showed that the expression levels of ER stress markers, including GRP78, PERK, IRE1α, ATF6, ATF4, XBP1S and CHOP, significantly increased with increasing concentration and duration of sorafenib treatment, suggesting that sorafenib can induce ER stress in liver cancer cells." (PMID 31523192, 2019).
squamous carcinoma (9 papers, 2015 to 2025). "Both pyocyanin and 1-HP decreased viability of RPMI2650s and other squamous carcinoma cell lines over 24 h, whereas HNECs survived, possibly due to differential regulation of protein homeostasis genes, including activating transcription factor 6 (ATF6)." (PMID 41416815, 2025). "Our identification of the mechanism by which Ceapins achieve their remarkable specificity forms a foundation to explore the utility of ATF6α inhibition in the treatment of cancers, such as squamous carcinomas, in which ATF6α signaling protects dormant tumor cells from classical chemotherapies." (PMID 31149896, 2019). "ATF6 modulates cancer cell dormancy via the activation of Ras homolog enriched in brain (RHEB) and mTOR, in which ATF6 not only plays a role as a key survival factor for quiescent squamous carcinoma cells, but is also pivotal for the adaptation of dormant cells to chemotherapy." (PMID 31739582, 2019). "ATF6 has been shown to be an important survival factor in dormant squamous carcinoma cells." (PMID 31739582, 2019). "Furthermore, ATF6α-mediated activation of Rheb and mTOR signalling promotes survival of dormant human squamous carcinoma cells (D-HEp3 cells) and their adaptation to chemotherapy and the in vivo microenvironment." (PMID 29801500, 2018). "Interestingly, activation of ATF6α-Rheb-mTOR pathway promotes survival of quiescent squamous carcinoma cells and subsequent adaptation to chemotherapy." (PMID 28835710, 2017). "Furthermore, activation of ATF6α and PERK have been shown to be essential for the long-term survival of dormant HEp-3 cells (Human Epidermoid carcinoma) derived from a cervical lymph node (metastatic site) from a buccal mucosa squamous cell carcinoma (primary site) in vitro and in vivo." (PMID 31151143, 2019).